MSLN (mesothelin)
Diseases named in the same sentence as MSLN in open-access papers (continued):
Sharing a sentence is not in itself a finding about the gene and the disease.
cervical carcinoma (continued). "In contrast, tissue sections derived from two cervical cancer patients (Tumor #1 and Tumor #3) showed high expression, while one tissue section (Tumor #2) showed low expression of Mesothelin." (PMID 39781381, 2024). "These analyses showed that the cytotoxic activity of anti-Mesothelin CAR-NK-92 cells against the cervical cancer cells was initiated early after initiating co-culture." (PMID 39781381, 2024). "Our findings indicate the promise of anti-Mesothelin CAR-NK cells as a potential treatment option against cervical cancer, as well as other Mesothelin+ malignancies." (PMID 39781381, 2024). "Among the upregulated proteins with the highest FC, we identified several proteins related to cervical cancer, such as MSLN (mesothelin), a cell surface glycoprotein linked to a role in cell adhesion." (PMID 36992411, 2023). "In our study, MSLN expression was observed in 98.4% of patients with cervical cancer, with MSLN being highly expressed in 63.4% of them." (PMID 36434635, 2022). "Cancer therapies targeting MSLN have been developed in recent years; however, the available information on MSLN expression in cervical cancer is limited." (PMID 36434635, 2022). "Another study that used anti-MSLN antibodies (clone 5B2) found that approximately 60% of patients with cervical cancer express MSLN, with its expression being lower in SCC than in adenocarcinoma (AC)." (PMID 36434635, 2022). "A correlation has been observed between MSLN expression in primary and metastatic lesions in cervical cancer." (PMID 36434635, 2022). "This study aimed to evaluate MSLN expression in various histological types of cervical cancer and examine its relationship with prognosis." (PMID 36434635, 2022). "The KB-3-1 cell line is a human cervical carcinoma cell line reported to express MSLN on its surface." (PMID 29738555, 2018). "This review outlines promising tumor-associated antigens (TAAs) for ADC targeting in cervical cancer and their biological functions, such as human epidermal growth factor receptor 2 (HER2), trophoblast cell surface antigen 2 (Trop-2), mesothelin, nectin cell adhesion molecule 4 (Nectin-4)." (PMID 40697656, 2025). "While these results demonstrated strong specificity of the CAR-NK-92 cells to target Mesothelin-expressing cervical cancer cells, this data also suggest the presence of immune evasion mechanisms that lead to resistance of these tumor models to NK-92 and CAR-NK-92 cell therapy." (PMID 39781381, 2024). "Few studies have evaluated MSLN expression in patients with cervical cancer." (PMID 36434635, 2022). "Thus, we aimed to evaluate MSLN expression in cervical cancer of various histological types using anti-MSLN antibodies (clone SP74) and to further examine the prognosis and changes in its expression in paired metastatic tumours." (PMID 36434635, 2022). "Collectively, these findings may motivate further investigation of MSLN-targeted therapy for patients with cervical cancer." (PMID 36434635, 2022). "Over 60% of patients with cervical cancer exhibited high MSLN expression levels." (PMID 36434635, 2022). "Our findings indicate that MSLN may be an attractive therapeutic target for cervical cancer." (PMID 36434635, 2022). "Several antigens, including GD2, PSMA, Muc1, and mesothelin, have been targeted in CAR‐T cell therapies for cervical cancer (ClinicalTrials.gov identifiers: NCT03356795 and NCT01583686)." (PMID 40525700, 2025). "Thus, MSLN may play a role in chemoresistance and tumour progression in cervical cancer." (PMID 36434635, 2022). "A phase I/II study (NCT03356795) evaluates the safety and efficacy of CAR T cells in cervical cancer patients whose tumour cells express TAAs such as GD2, PSMA, Muc1 or mesothelin." (PMID 33205441, 2021). "Next, we checked the Cervical Cancer Database (CCDB) and found three genes, haemoglobin alpha 2 (HBA2), mesothelin (MSLN) and STK11, overlapped between 849 genes/loci observed from our current study and 538 genes listed in the CCDB." (PMID 29083376, 2016).
cervical carcinoma (continued). "As cisplatin continues to be a main component of treatment regimens for cervical cancer, it is of interest to identify novel approaches, such as anti-Mesothelin CAR-NK-92 cells, that can be applied in combination with cisplatin with the aim to potentiate the elimination of cervical cancer cells." (PMID 39781381, 2024). "Notably, the anti-Mesothelin CAR-NK-92 cells generated in our study decreased spheroid integrity and eliminated cervical cancer cells even in this 3D model." (PMID 39781381, 2024). "Other ongoing studies include a TCR-T therapy targeting EBV, developed by TCRCure Biopharma, for metastatic head and neck cancer and cervical cancer, as well as TC-510, developed by TCR2 Therapeutics, which targets mesothelin for the treatment of late-stage mesothelin-expressing cancers." (PMID 39439803, 2024). "In contrast, CARMz T cells efficiently lysed HeLa-GL cells, a cervical cancer cell line that spontaneously expresses MSLN but not PD-L1, and was engineered to express GFP and luciferase (GL)." (PMID 36229619, 2022). "High MSLN expression was substantially more frequent in non-SCC than in SCC and was associated with poor prognosis in patients with cervical cancer of common histological types." (PMID 36434635, 2022). "Our results indicate that addition of mesothelin to the TR3 domain as in Meso-TR3, increases the effectiveness of TR3 in MUC16-positive malignancies such as ovarian and cervical cancers (shown for OVCAR3 and HeLa cell lines), while limiting its bioactivity on MUC16-negative Jurkat cells." (PMID 24447304, 2014). "Interestingly, we observed low or no expression of Mesothelin in healthy cervical tissue sections, but high expression in most of the analyzed cervical cancer samples." (PMID 39781381, 2024). "Additionally, we investigated the Mesothelin expression on sections derived from primary cervical cancer tissues and from a non-cancerous healthy sample." (PMID 39781381, 2024). "MSLN was highly expressed in patients with cervical cancer, especially in those with non-SCC." (PMID 36434635, 2022).
non-small cell lung carcinoma (19 papers, 2015 to 2025). A group of at least three distinct histological types of lung cancer, including non-small cell squamous cell carcinoma, adenocarcinoma, and large cell carcinoma. "They identified a panel of seven glycopeptides, including mesothelin, who performs better than mesothelin alone in detecting MPM vs. non-small cell lung cancer (NSCLC) or pleural benign disease (sensitivity 91% vs. 74%, specificity 78% vs. 74%)." (PMID 36046389, 2020). "FGM profiling showed MSLN overexpression in gastrointestinal (12–36%) and gynecological tumors (20–66%), non-small cell lung cancer (21%) and synovial sarcomas (30%)." (PMID 26172299, 2015). "Notably, combined mesothelin and CEA enhanced the diagnostic accuracy in distinguishing MPM from non-small cell lung cancer (NSCLC)." (PMID 28403901, 2017).
Pleural effusion (19 papers, 2010 to 2025). The presence of an excessive amount of fluid in the pleural cavity. "Although mesothelin bounds to cell membrane, a circulating form termed soluble mesothelin can be detected in the blood and pleural effusion by using enzyme-linked immunosorbent assay (ELISA)." (PMID 28507279, 2017). "Using logistic regression models, we have recently demonstrated that a combination of mesothelin and the microRNA miR-103a-3p in blood as well as the combination of mesothelin and hyaluronic acid in pleural effusion were able to improve the diagnostic accuracy of the assays." (PMID 28558669, 2017). "However, Creany and associates found that although fibulin-3 is highly expressed in MPM, its diagnostic power as a plasma or pleural effusion biomarker is less than that of mesothelin." (PMID 28403901, 2017). "Therefore, mesothelin would be an unsuitable diagnostic marker in an accumulative pleural effusion." (PMID 20628387, 2010). "Soluble mesothelin have been measured in both pleural effusion and serum, but the low sensitivity has so far prevented its widespread use as screening tool." (PMID 36765599, 2023). "Pleural effusion Galectin-1, NRG1-β1, Osteopontin, Mesothelin, shed SDC-1, VEGF and TIMP-1 levels are more reliable diagnostic biomarkers than HGF and MMP in pleural effusion." (PMID 32731396, 2020). "ROC analysis of this cohort revealed that serum Mesothelin had the highest predictive value (AUC: 0.94) followed by pleural fluid Mesothelin (AUC: 0.89) and DNA integrity index in pleural effusion (AUC: 0.82)." (PMID 31475103, 2019). "Mesothelin concentrations in pleural effusions from patients with MM (28 ± 4.3 nM) were significantly higher than those from patients with benign effusions (3.2 ± 3 nM; P < 0.0001) and patients with non-MM malignancies (4.7 ± 3.9 nM; P < 0.0001)." (PMID 25505814, 2014). "In a subset analysis of 77 cases where an effusion sample was available before or within one week of a biopsy confirming a diagnosis of MM (which included 7 sarcomatoid and 16 biphasic cases) pleural effusion mesothelin levels were elevated in 51 (66%) cases." (PMID 25505814, 2014). "The combined analysis of hyaluronan and C-ERC/mesothelin in pleural effusions has previously been reported in a small set of patients, concluding that there was little or no interest in combining the two." (PMID 23991032, 2013). "Here we found that serum mesothelin provided the highest area under the ROC curve (0.94, 95% CI 0.87-1.00) followed by pleural fluid mesothelin (0.89, 95% 0.77-1.00) and pleural effusion DNA integrity index (0.82, 95% CI 0.68-0.97)." (PMID 23009708, 2012). "Hyaluronic acid and soluble mesothelin have been known as diagnostic markers for MPM in pleural effusion and plasma, respectively." (PMID 20628387, 2010). "utilised pleural effusion samples collected from 1,331 MM patients, whereby it was established that effusion-derived mesothelin exhibits a 95% specificity for MM; justifying the clinical utility of pleural effusion-derived mesothelin as a biomarker to facilitate a definitive diagnosis of MM." (PMID 34900693, 2021). "Of the 1331 pleural effusion samples received from each individual, 936 were reported as being nondiagnostic, nonmalignant, atypical, or suspicious of malignancy (i.e., 855 + 81 = 936); mesothelin level was elevated in 53 (i.e., 5.7%) of these samples." (PMID 25505814, 2014). "In this work, we confirmed the deregulation of CFB, MSLN and CLDN15 on pleural effusions from epithelioid and biphasic PM." (PMID 38067238, 2023). "In order to evaluate the correlation between ELISA and Luminex immunoassays, pleural effusion levels of shed SDC-1, Mesothelin and VEGF were measured independently by both immunoassays." (PMID 32731396, 2020).
Pleural effusion (continued). "In order to determine the prognostic value of pleural effusion derived Angiopoietin-1, HGF, MMP-7, Osteopontin, TIMP-1, Galectin, Mesothelin, NRG1-b1, SDC-1 and VEGF, we divided patients in two groups depending on the established cut-off value for all analytes." (PMID 32731396, 2020). "A mesothelin-positive pleural effusion, irrespective of the identification of malignant cells, indicates the likely presence of malignancy and adds weight to the clinical rationale for further investigation to establish a malignant diagnosis." (PMID 25505814, 2014). "Moreover, there is a negative correlation between Mesothelin and shed SDC-1 and positive correlation between VEGF, Angiopoietin-1 and shed SDC-1 level in the pleural effusion from malignant cases." (PMID 32731396, 2020).
epithelioid mesothelioma (18 papers, 2008 to 2025). "These histologic features as well as increased expression of Mesothelin are associated with better prognosis in patients with epithelioid mesothelioma." (PMID 37761312, 2023). "Our data also confirmed that higher MSLN expression is associated with improved patient survival in epithelioid mesothelioma." (PMID 37040900, 2023). "Conversely, the mesothelial marker, calretinin, can be coexpressed with MSLN in epithelioid mesothelioma, but its association with prognosis and atypia is unclear." (PMID 37040900, 2023). "One of the hub genes in this module is MSLN, encoding mesothelin, a well-characterized biomarker for mesothelial tissue, and commonly overexpressed in epithelial mesotheliomas." (PMID 32824422, 2020). "In epithelioid mesothelioma, MSLN demonstrates high expression levels and can serve as an ancillary diagnostic marker for this subtype; conversely, sarcomatoid mesothelioma typically displays relatively low MSLN expression." (PMID 41400642, 2025). "Given the high expression of MSLN in epithelial mesothelioma, a range of innovative treatment strategies are currently being evaluated in various phases of clinical trials." (PMID 40362535, 2025). "MSLN immunostaining in an Australian cohort with epithelioid mesothelioma demonstrated inter‐patient heterogeneity of expression." (PMID 37040900, 2023). "Membranous staining with fainter cytoplasmic staining was the most common MSLN immunostaining pattern in epithelioid mesothelioma." (PMID 37040900, 2023). "Mesothelin (MSLN) is a glycoprotein with high expression in epithelioid mesothelioma and low expression in normal tissues, thereby it represents an attractive target for several therapies." (PMID 32226777, 2020). "Epithelioid mesothelioma showed significantly higher mesothelin expression (81% with 5B2 and 84% with MN-1) than sarcomatoid (20% with 5B2 and 20% with MN-1) and biphasic (65% with 5B2 and 65% with MN-1) histotypes with both antibodies." (PMID 28460459, 2017). "Immunohistochemistry staining of a human epithelial mesothelioma sample was then carried out using these antibodies and a positive control against MSLN." (PMID 21984916, 2011). "MSLN expression was more heterogenous in epithelioid mesothelioma than reported previously." (PMID 37040900, 2023). "Finally, when assessing the intensity of MSLN immunostaining, the values of moderate (2+) or strong (3+) intensity immunostaining by IHC vary between 52%13 and 70%27 in epithelioid mesothelioma." (PMID 37040900, 2023). "It is noteworthy that 60% of effusions from sarcomatous mesothelioma showed high sCD157 concentrations, while mesothelin proved to be a useful marker for epithelioid mesothelioma but not for other histological variants." (PMID 29854315, 2018). "Approximately 77% of patients with epithelial mesothelioma tested positive for MSLN, a finding not observed in sarcomatoid tumors." (PMID 40362535, 2025). "In addition, all 15 cases of epithelial mesothelioma, but none of the 4 cases of sarcomatous mesothelioma, expressed MSLN." (PMID 31463062, 2019).
hepatocellular carcinoma (13 papers, 2014 to 2025). A malignant tumor that arises from hepatocytes. "CAR-T cells against tumor-specific antigens (TSA), including mesothelin (MSLN) and glypican 3 (GPC3) are being actively tested for treating non-small-cell lung cancer (NSCLC) and hepatocellular carcinoma, respectively." (PMID 32514352, 2020). "In addition to pancreatic carcinoma, a recent study shows that mesothelin, a mesothelial marker, is also found in 33% of resected CC specimens, but not hepatocellular carcinoma (HCC) or normal liver tissue." (PMID 24860692, 2014).
glioblastoma (12 papers, 2017 to 2025). The most malignant astrocytic tumor (WHO grade IV). "Targeted therapy with HER2 and EGFRvIII has improved survival in preclinical models and is expected to breach the blood‒brain barrier, whereas IL-13Rα2 and MSLN have been shown to be potential targets for tumor clearance in brain tumors such as glioblastoma (GBM)." (PMID 40850976, 2025). "Emerging topics in this field mainly include the study of CAR-T cells in glioblastoma (related targets: IL13Rα2, EGFRvIII, and HER2), neuroblastoma (related target: GD2), sarcoma (related target: HER2), and pancreatic cance (related target: mesothelin), especially glioblastoma." (PMID 35371087, 2022). "EGFR-target TAAs in glioblastoma (GBM), HER2-target TAAs in GBM and sarcoma, and MSLN-target TAAs in mesothelioma have all demonstrated an effective on-target therapeutic response with increased overall survival leading to the development of clinical trials." (PMID 29546043, 2018).
squamous cell carcinoma (12 papers, 2008 to 2025). A carcinoma arising from squamous epithelial cells. "A previous report showed that 42.4% of 125 patients with squamous cell carcinoma (SCC) of the cervix expressed MSLN using anti-MSLN antibodies (MSVA-235)." (PMID 36434635, 2022). "Squamous cell carcinomas of various different sites of origin represent the next group of cancers that show MSLN expression at a relatively high frequency (10–40%)." (PMID 33917081, 2021). "The A431/H9 cell line is an A431 (human epidermoid carcinoma) cell line transfected to stably overexpress MSLN on its surface." (PMID 29738555, 2018). "Mesothelin was detected in the A-253 cells and the surgical specimens except for the case of squamous cell carcinoma to various degrees." (PMID 30558663, 2018). "The SGCs, which we examined, expressed MSLN except for the case of squamous cell carcinoma that is a rare in SGC." (PMID 30558663, 2018). "We observed that MSLN amplification rate within esophageal cancer depends on the histotype (31% for adenocarcinomas versus 3% for squamous-cell carcinomas)." (PMID 26172299, 2015). "In addition, we observed that MSLN amplification rate within esophageal cancer depends on the histotype (31% for adenocarcinomas versus 3% for squamous-cell carcinomas)." (PMID 26172299, 2015). "However, according to a recent review article, mesothelin is positive in 27% of squamous cell carcinomas, and calretinin and cytokeratin 5/6 can be raised in both squamous cell carcinoma of the lung and adenocarcinoma of both the lung and other sites." (PMID 19099560, 2008). "Conversely, the expression of ERBB3, MSLN, and MUC-1 was markedly elevated in adenocarcinoma relative to squamous cell carcinoma." (PMID 40046734, 2025). "ERBB3, MSLN, and MUC-1 expression was markedly elevated in adenocarcinoma relative to squamous cell carcinoma." (PMID 40046734, 2025). "There was also a strong tendency towards higher MSLN expression in HPV positive than in HPV negative squamous cell carcinomas (p = 0.0098)." (PMID 33917081, 2021). "MSLN reactivity was observed in 78 of 148 (53%) adenocarcinomas, 29 of 124 (23%) squamous cell carcinomas and 15 of 118 (13%) large cell carcinomas but was absent in small cell carcinomas." (PMID 31463062, 2019).
acute myeloid leukemia (10 papers, 2015 to 2025). Acute myeloid leukemia (AML) is a group of neoplasms arising from precursor cells committed to the myeloid cell-line differentiation. "Overexpression of mesothelin has been reported in the bone marrow of 36% of acute myeloid leukemia (AML) patients." (PMID 38396817, 2024). "We show future directions for mesothelin targeting in hematological malignancies, including acute myeloid leukemia." (PMID 35326701, 2022). "Additionally, predicted MSLN amplifications were found in 9% of the renal cell carcinomas (N = 428 tumors), 5% of the thyroid cancers (N = 21 tumors), 5% of acute myeloid leukemias (N = 761 tumors) and 4% of the HNSCC (N = 356 tumors)." (PMID 26172299, 2015). "Emerging evidence demonstrates that in acute myeloid leukemia (AML) patients, MSLN is predominantly expressed in the CD45dim/SSC-Alow myeloid cell subpopulation and exhibits minimal expression in mature lymphocytes and monocytes." (PMID 41400642, 2025). "A similar concept was applied by combining a mesothelin CAR and a Folate receptor CCR to target ovarian cancer or combining a CD13 CAR and a TIM3 CCR to target acute myeloid leukemia (AML)." (PMID 36961206, 2023). "In addition, more CAR-T therapies targeting other cancers are under preclinical and clinical studies, such as mesothelin-targeting CAR-T cells to treat ovarian cancer, and CD70-targeting CAR-T cells to treat acute myeloid leukemia (AML)." (PMID 39851334, 2025).